NPAS4 (neuronal PAS domain protein 4)
Diseases named in the same sentence as NPAS4 in open-access papers (continued):
Sharing a sentence is not in itself a finding about the gene and the disease.
cognitive decline (4 papers, 2016 to 2025). "Our results showing an association of CPP learning and increases in Npas4 mRNA levels complement the decreases observed in cognitive decline." (PMID 29093669, 2017). "Reduced levels of Npas4 mRNA in hippocampus have previously been noted in aged rats 52, although this has not been specifically associated with the subset of animals showing cognitive decline." (PMID 26563879, 2016). "Increased Npas4 expression in the prefrontal cortex by theanine may be involved in the suppression of brain atrophy and cognitive decline in aged SAMP10 mice that ingested theanine." (PMID 31936294, 2020). "The ablation of circulating CD8+ T cells in APP/PS1 mice does not reduce the Aβ load or cognitive decline but increases the expression of neuronal genes such as Arc and Npas4, suggesting that brain CD8+ T cells may modulate synaptic plasticity." (PMID 40993111, 2025).
Alzheimer disease (3 papers, 2018 to 2025). A progressive, neurodegenerative disease characterized by loss of function and death of nerve cells in several areas of the brain leading to loss of cognitive function such as memory and language. "Additionally, NPAS-4 is thought to be involved in neuroinflammation and cell death processes associated with Alzheimer’s disease." (PMID 40563435, 2025). "NPAS-4 has been shown to function in various neurological and psychiatric disorders beyond Alzheimer’s disease." (PMID 40563435, 2025). "Therefore, the role of NPAS-4 in understanding synaptic losses and neuroinflammation in Alzheimer’s disease is becoming increasingly important." (PMID 40563435, 2025). "NPAS4 has also been shown to enhance autophagic clearance of the total and phosphorylated pools of endogenous Tau protein in primary cortical neurons, implicating NPAS4 as a potential therapeutic target for neurodegenerative tauopathies such as Alzheimer's disease." (PMID 29899116, 2018). "NPAS4 recently was shown to induce autophagy in rat primary cortical neurons and to degrade Tau proteins involved in the pathogenesis of Alzheimer's disease and other tauopathies through an unknown mechanism." (PMID 29899116, 2018). "Therefore, the possibility that NPAS-4 and NPTX-2 may serve as diagnostic and therapeutic biomarkers in Alzheimer’s disease warrants further investigation." (PMID 40563435, 2025). "Our findings support the hypothesis that NPAS-4 and NPTX-2 are involved in the pathophysiological process of Alzheimer’s disease and may serve as potential biomarkers for early diagnosis and monitoring of disease progression." (PMID 40563435, 2025).
autism spectrum disorder (3 papers, 2018 to 2023). A spectrum of developmental disorders that includes autism, and Asperger syndrome. "Indeed, mutations of genes encoding for subunits of the NPAS4-NuA4 complex have been described in neurodevelopmental and autism spectrum disorders." (PMID 37512859, 2023). "Cluster 3 proteins reported to have altered expression in autism spectrum disorders (ASD), that may consequently result from knockdown of activity regulated gene transcription mediated by Npas4." (PMID 29915698, 2018).
Brain atrophy (3 papers, 2020 to 2022). Partial or complete wasting (loss) of brain tissue that was once present. "Increased expression of Npas4 is considered to be important for preventing brain atrophy due to stress." (PMID 31936294, 2020). "Theanine was suggested to prevent stress-induced brain atrophy by modifying early stress responses such as Npas4 and Lcn2." (PMID 31936294, 2020). "The difference between SAMP10 and ddY mice regarding the expression of Npas4 is considered to contribute to the difference in the degree of brain atrophy." (PMID 31936294, 2020). "Although brain atrophy in Npas4 knockout mice is not mentioned, increased Npas4 expression during stress appears to be needed to increase stress tolerance." (PMID 31936294, 2020).
neuroblastoma (3 papers, 2014 to 2023). Neuroblastoma (NB) is the most common solid, extracranial childhood tumor. "Firstly, N2A cells from murine neuroblastoma were divided into two groups and then co-transfected with pGL4.10-Nlrp6 promotor(fLuc) and pGL4.74(rLuc), respectively, together with NPAS4 overexpression plasmids (pIRES2-Npas4-Flag) or empty vector plasmids (EV-Ctrl)." (PMID 37176030, 2023).
glioma (2 papers, 2021 to 2024). A benign or malignant brain and spinal cord tumor that arises from glial cells (astrocytes, oligodendrocytes, ependymal cells). "In glioma grade III, highly activated DEGs included CFAP45, PLBD1, RASSF9, IGKV3-11, IGKV1-5, and NTS, while highly downregulated DEGs included NPAS4 and LINC01007." (PMID 33948562, 2021).
mood disorder (2 papers, 2017 to 2022). A cognitive disorder a disturbance in which the person's mood is hypothesized to be the main underlying feature. "It is known that NPAS4 is significantly downregulated in the hippocampus and prefrontal cortex of SERT-/- rats, a mammalian model for mood disorders." (PMID 35573988, 2022). "Because some IEGs are induced more sparsely compared to others (e.g., NPAS4), the relevance of IEG expression to mood disorders may be tied to their induction in specific cell populations." (PMID 28503137, 2017).
post-traumatic stress disorder (2 papers, 2021 to 2022). An anxiety disorder precipitated by an experience of intense fear or horror while exposed to a traumatic (especially life-threatening) event. "Moreover, increased Npas4 expression suppresses fear memory in a post-traumatic stress disorder (PTSD) mouse model, further highlighting the importance of inhibitory signaling related to psychological disorders." (PMID 35955487, 2022).
status epilepticus (2 papers, 2014 to 2017). Status epilepticus is defined as a continuous seizure lasting more than 30 min, or two or more seizures without full recovery of consciousness between any of them. "Real-time PCR analysis showed the expected higher levels of Arc, FosB, Inhba, Npas4, Pchd8 and Tll1 bound to Upf1 after status epilepticus whereas levels of Slc1a2 were not different between groups." (PMID 28128343, 2017).
behavioral disorders (1 paper, 2025). "In mouse models where the NPAS-4 gene is completely deleted, various behavioral disorders such as hyperactivity, reduced social interaction, loss of cognitive flexibility, and impaired pre-pulse inhibition have been reported." (PMID 40563435, 2025).
coronary heart disease (1 paper, 2024). "However, there are studies showing that Npas4 polymorphisms contribute to the cardiovascular diseases risk (coronary heart disease)." (PMID 38928385, 2024).
dementia (1 paper, 2014). Loss of intellectual abilities interfering with an individual's social and occupational functions. "Our results now seem to warrant targeted sequencing of NPAS4 in cohorts of neuropsychiatric and/or dementia patients." (PMID 24465693, 2014).
developmental delays (1 paper, 2021). "Here we have identified loss-of-function variants in both NPAS3 and NPAS4 in individuals with ID and developmental delay respectively, further establishing them as candidate neurodevelopmental disorder genes." (PMID 33758288, 2021). "The NPAS4 170X variant is the first identified loss-of-function allele for NPAS4 in an individual with developmental delay." (PMID 33758288, 2021). "In summary, two loss-of-function variants NPAS3 214fs and NPAS4 170X, were identified in individuals with either ID or developmental delay." (PMID 33758288, 2021). "From a clinical exome sequencing database we identified three NPAS3 variants and four NPAS4 variants that could potentially disrupt protein function in individuals with either developmental delay or ID." (PMID 33758288, 2021). "Similarly, the older individuals with NPAS4 E99K and R145H variants have been diagnosed with ID, whereas the younger individuals with the G59D and 170X variants have been diagnosed with developmental delays." (PMID 33758288, 2021). "Therefore, we identified individuals from a clinical exome sequencing database who possessed a NPAS3 or NPAS4 variant that may reduce transcriptional activity and a phenotype that included either ID or developmental delay." (PMID 33758288, 2021). "Therefore, we have identified the first variant in NPAS4 identified in an individual with developmental delay, as well as the third NPAS3 variant in an individual with developmental delay/ID, further establishing NPAS3 and NPAS4 as candidate neurodevelopmental disorder genes." (PMID 33758288, 2021).
diabetes (1 paper, 2023). "Studies showed that observed in the course of diabetes, the decreased tissue glucose uptake, increased insulin resistance, and accelerated neuronal dysfunction are associated with the strong decline of Snca, Arc, and Npas4 genes expression levels." (PMID 36869919, 2023).
hematoma (1 paper, 2023). A hematoma is a collection of blood from a vascular structure into an extravascular space. "Representative pictures of immunohistochemical staining showed that the expression of NPAS4 was significantly increased around the hematoma tissues of patients with ICH compared with that in controls (p < 0.01)." (PMID 37176030, 2023). "Firstly, our data showed that NPAS4, which is highly expressed in neurons, was upregulated in human and mouse peri-hematoma brain tissues and peaked at approximately 24 h after ICH modeling." (PMID 37176030, 2023). "In this study, we found that NPAS4 protein levels were increased in human and mouse peri-hematoma brain tissues." (PMID 37176030, 2023). "In this study, we found that NPAS4 was upregulated in human and mouse peri-hematoma brain tissues and peaked at approximately 24 h after ICH modeling." (PMID 37176030, 2023). "Moreover, fewer MPO-positive cells were found around the hematoma in the ICH + NPAS4-siRNA group than in the ICH group (p < 0.05), which revealed that NAPS4 deficiency could reduce the infiltration degree of neutrophils." (PMID 37176030, 2023).
Hypertension (1 paper, 2024). The presence of chronic increased pressure in the systemic arterial system. "In the hypothalamus of WAG rats, Npas4 gene expression correlates statistically most significantly with the expression of other DEGs, among which the Bcl2l1 gene is associated with hypertension and four DEGs encode TFs (Isl1, Hnrnpr, Mlxipl, and Zfp189)." (PMID 38928385, 2024). "In the hypothalamus of ISIAH rats, Npas4 gene expression correlates statistically most significantly with the expression of Jun and Fos genes, which are associated with hypertension and encode TFs." (PMID 38928385, 2024). "The limitations of our study include the fact that the results, while suggesting a significant role of the Npas4 gene in the regulation of the response to stress, do not allow us to associate changes in its activity with hypertension." (PMID 38928385, 2024). "The association of Npas4 gene expression with hypertension has not yet been established in other hypertensive animal models." (PMID 38928385, 2024).
intracerebral hemorrhage (1 paper, 2023). A cerebrovascular disorder characterized by bleeding into one or both cerebral hemispheres including the basal ganglia and the cerebral cortex. "In summary, in this study, we have demonstrated the role and underlying mechanism of NPAS4 in the acute phase of intracerebral hemorrhage in mice." (PMID 37176030, 2023). "In summary, this study investigated the role and potential mechanism of NPAS4 in a brain injury after intracerebral hemorrhage in mice." (PMID 37176030, 2023). "In follow-up experiments, Nlrp6−/− mice should be raised to further explore the interaction of NPAS4 with the NLRP6 inflammasome in order to determine the potential mechanism of NPAS4 after intracerebral hemorrhage." (PMID 37176030, 2023). "However, the role of NPAS4 in the acute phase of intracerebral hemorrhage in mice still remains unknown." (PMID 37176030, 2023). "Therefore, this study was designed to explore whether NPAS4 affects intracerebral hemorrhage and interacts with the Nlrp6 promoter." (PMID 37176030, 2023). "Altogether, our study demonstrated that NPAS4, as a transcription factor, can exacerbate pyroptosis and transcriptionally activate NLRP6 in the acute phase of intracerebral hemorrhage in mice." (PMID 37176030, 2023). "Additionally, it also confirmed that NPAS4 might aggravate pyroptosis and brain injury via activating the NLRP6 inflammasome after intracerebral hemorrhage in mice." (PMID 37176030, 2023).
leiomyoma (1 paper, 2022). A well-circumscribed benign smooth muscle neoplasm characterized by the presence of spindle cells with cigar-shaped nuclei, interlacing fascicles, and a whorled pattern. "The promoter regions of NPAS4 and PITX1 genes were selected as the candidate methylation marker loci to distinguish uterine leiomyosarcoma and leiomyoma." (PMID 35875106, 2022).
Obesity (1 paper, 2026). Accumulation of substantial excess body fat. "Indeed, we found several variants in clinical databases or from previous early onset obesity cohorts which are predicted to disrupt PAS-loop-mediated DNA binding in NPAS4, HIF2α, or SIM1." (PMID 41495897, 2026).
sarcopenia (1 paper, 2020). Progressive decline in muscle mass due to aging which results in decreased functional capacity of muscles. "Therefore, we focused on the determination of the single and combined effect of MTHFR, ACTN3, NRF2, VDR FokI, ADRB2, and NPAS4 polymorphism associated with sarcopenia in older adults." (PMID 33505434, 2020).
sleep disorder (1 paper, 2021). A change from the patient's baseline sleeping pattern, in the hours slept and/or an alteration/dysfunction in the stages of sleep. "Our data suggests that the alterations of genes associated with circadian rhythm such as Per2 and Npas4 due to the influences of ELS may trigger sleep disorders." (PMID 34795694, 2021).
viral infection (1 paper, 2021). "We observed that the expression levels of transcription factors such as neural PAS domain protein 4 (Npas4) and of three members of the orphan nuclear receptor 4 (Nr4a) were severely decreased after viral infection." (PMID 34048439, 2021).
ZIKV infection (1 paper, 2021). "In conclusion, our results show that ZIKV infection induces an aberrant downregulation of the neural transcription factors Npas4 and Nr4as that affect the generic transcription pathway in neurons." (PMID 34048439, 2021). "We identified that neural PAS domain protein 4 (Npas4) and the orphan nuclear receptor 4 (Nr4a) transcription factors were profoundly modulated upon ZIKV infection." (PMID 34048439, 2021). "Moreover, Npas4 and Nr4a3 were also significantly downregulated at the protein level following ZIKV infection." (PMID 34048439, 2021).
neurodegenerative disease (7 papers, 2014 to 2023). A disorder of the central nervous system characterized by gradual and progressive loss of neural tissue and neurologic function. "NPAS4 has therefore been implicated in a number of neuropsychiatric or neurodegenerative diseases which are underpinned by defects in excitatory/inhibitory balance." (PMID 24465693, 2014). "Mice lacking NPAS4 exhibit many hallmarks of both neuropsychiatric and neurodegenerative diseases, but as yet this transcription factor has not been linked to any human disorder." (PMID 24465693, 2014). "Altogether, these studies position Npas4 and BDNF as outstanding therapeutic targets against AβOs-induced synaptotoxicity and may constitute targets to prevent the development of AD and other neurodegenerative diseases." (PMID 38001825, 2023).
psychiatric disorder (6 papers, 2012 to 2025). A disorder characterized by behavioral and/or psychological abnormalities, often accompanied by physical symptoms. "Furthermore, dysfunction or alterations in these IEGs are frequently associated with aging and various neurological and psychiatric diseases, and Npas4, Zif268, and Narp have been implicated in addiction and addictive behaviors." (PMID 40715999, 2025). "We hypothesized that alterations in the inhibitory pathways induced by the absence of Npas4 play a major role in the expression of the symptoms observed in psychiatric disorders." (PMID 23029555, 2012).
neurodevelopmental disorder (4 papers, 2018 to 2023). A behavioral and cognitive disorder with onset during the developmental period that involves impaired or aberrant development of intellectual, motor, or social functions. "The identification of additional NPAS3 and NPAS4 variants will further our understanding of rare variants that may contribute to SZ or neurodevelopmental disorders which could then assist in patient diagnosis." (PMID 33758288, 2021). "Therefore, more work is needed to identify NPAS4 variants that are linked to SZ or neurodevelopmental disorders." (PMID 33758288, 2021). "Therefore, the identification of causative NPAS4 neurodevelopmental disorder alleles may be complicated by variable penetrance." (PMID 33758288, 2021). "The goal of the present study is to further investigate the potential role of Npas4 in prefrontal PV+ neurons deregulation and behavioral impairments as seen in some neurodevelopmental disorders." (PMID 30792384, 2019). "This further establishes NPAS3 and NPAS4 as candidate neurodevelopmental disorder genes." (PMID 33758288, 2021). "A recent report supported our conclusions that Npas4 could be a contributor to the molecular and behavioral abnormalities seen in neurodevelopmental disorders characterized by abnormal functioning of the prefrontal PV system." (PMID 30792384, 2019). "Protein-protein interaction analysis revealed NPas4 interaction with various proteins which are mainly involved in nuclear trafficking of proteins to cytoplasm, activity regulated gene transcription and neurodevelopmental disorders." (PMID 29915698, 2018). "To date, the involvement of NPAS3 and NPAS4 in neurodevelopmental disorders has not been extensively explored." (PMID 33758288, 2021).
Neurological Disease (4 papers, 2012 to 2020). "Here we will further summarize the associated research progress on Npas4 functions in nervous system diseases." (PMID 33335473, 2020). "NPAS4 is a transcription factor critical for maintaining homeostatic balance of excitation/inhibition within neurons and has been implicated in several neurological diseases." (PMID 24465693, 2014). "This suggests that the transcription factor Npas4 may play a major role in the regulation of cognitive and social functions in the brain with possible implication for neurological disorders." (PMID 23029555, 2012).
infection (3 papers, 2013 to 2021). The state of being infected such as from the introduction of a foreign agent such as serum, vaccine, antigenic substance or organism. "BDNF is reduced in neurons with decreased levels of NPAS4 after lentiviral NPAS4-shRNAi infection and primary cell cultures from NPAS4 knockout mice consistently show a similar reduction of depolarization-induced BDNF expression." (PMID 24024041, 2013). "This could be complemented by studies of plasticity in wild-type animals after NPAS4 downregulation by selective NPAS4-shRNAi infection or in NPAS4flx/flx mice with a selective deletion of the NPAS4 gene by CRE recombination in the developing visual cortex." (PMID 24024041, 2013). "This phenomenon seems to underlie, at least partially, the effect of NPAS4 in increasing the formation of inhibitory synapses, as the number of inhibitory synaptic contacts induced by NPAS4 is moderately attenuated in cells in which BDNF has been knocked down by BDNF-shRNAi infection." (PMID 24024041, 2013). "This scenario, however, seems to be unlikely as there is evidence that knocking down NPAS4 expression by NPAS4-shRNAi infection in the visual cortex of naïve animals does not restore visual cortex susceptibility to monocular deprivation in adult life." (PMID 24024041, 2013).